UGT1A9 (UDP glucuronosyltransferase family 1 member A9)
Description:
[Isoform 1]: UDP-glucuronosyltransferase (UGT) that catalyzes phase II biotransformation reactions in which lipophilic substrates are conjugated with glucuronic acid to increase the metabolite's water solubility, thereby facilitating excretion into either the urine or bile. Essential for the elimination and detoxification of drugs, xenobiotics and endogenous compounds. Catalyzes the glucuronidation of endogenous estrogen hormones such as estradiol and estrone. Involved in the glucuronidation of arachidonic acid (AA) and AA-derived eicosanoids including 15-HETE, PGB1 and F2-isoprostanes (8-iso-PGF2alpha and 5-epi-5-F2t-IsoP). Glucuronates the phytochemical ferulic acid efficiently at both the phenolic or the carboxylic acid group. Also catalyzes the glucuronidation of the isoflavones genistein, daidzein, glycitein, formononetin, biochanin A and prunetin, which are phytoestrogens with anticancer and cardiovascular properties. Involved in the glucuronidation of the AGTR1 angiotensin receptor antagonist caderastan, a drug which can inhibit the effect of angiotensin II. Involved in the biotransformation of 7-ethyl-10-hydroxycamptothecin (SN-38), the pharmacologically active metabolite of the anticancer drug irinotecan. Also metabolizes mycophenolate, an immunosuppressive agent. [Isoform 2]: Lacks UGT glucuronidation activity but acts as a negative regulator of isoform 1.
Synonyms: UDPGT 1-9; UGT1-09; UGT1.9; UGT-1I; UGT1I; HLUGP4; LUGP4; UGT1AI; UDPGT; UGT1-9; UGT1A9S
Tractability: Small molecule: a high-quality ligand is known. Antibody: UniProt predicts a signal peptide or a membrane-spanning region. PROTAC: its protein half-life has been measured.
Target class: Enzyme; Transferase
Safety:
Unwanted effects reported when the protein is acted on. In parentheses: how it was acted on, where the effect was seen, and who reports it.
a diminished estimated glomerular filtration rate and transient proteinuria (source: ClinPGx)
adverse drug reactions (source: ClinPGx)
adverse effects (source: ClinPGx)
adverse reactions (source: ClinPGx)
better response (source: ClinPGx)
cardiotoxicity (source: ClinPGx)
diminished estimated glomerular filtration rate and transient proteinuria (source: ClinPGx)
hand-foot syndrome (source: ClinPGx)
hyperbilirubinemia (source: ClinPGx)
hyperprolactinemia (source: ClinPGx)
liver failure (source: ClinPGx)
nephrolithiasis (source: ClinPGx)
neutropenia (source: ClinPGx)
severe neutropenia (source: ClinPGx)
worse response (source: ClinPGx)
Gene: Protein-coding gene on chromosome 2 (233,671,898 to 233,773,300, forward strand). Ensembl gene ENSG00000241119.
Subcellular location: Endoplasmic reticulum membrane
Pathways (Reactome):
Drug ADME: Aspirin ADME; Paracetamol ADME
Metabolism: Glucuronidation; PPARA activates gene expression
Gene Ontology:
Molecular function: enzyme binding; glucuronosyltransferase activity; protein homodimerization activity; retinoic acid binding; enzyme inhibitor activity; protein heterodimerization activity; UDP-glycosyltransferase activity
Biological process: flavone metabolic process; flavonoid metabolic process; xenobiotic metabolic process; cellular response to glucocorticoid stimulus; estrogen metabolic process; liver development; retinoic acid metabolic process; monocarboxylic acid metabolic process
Cellular component: endoplasmic reticulum; endoplasmic reticulum membrane
Genetic constraint (gnomAD): Loss-of-function variants: 35 observed, 46.46 expected, observed/expected ratio (o/e) 0.75, 90% interval 0.57 to 1. The upper end of that interval is the gene's LOEUF score, 1, which puts it in group 4 of 6, group 1 being the genes least tolerant of losing a copy. Missense variants: 687 observed, 694.64 expected, observed/expected ratio (o/e) 0.99, 90% interval 0.93 to 1.05. Synonymous variants: 278 observed, 264.15 expected, observed/expected ratio (o/e) 1.05, 90% interval 0.95 to 1.16.
Homologues: Orthologues: dog UGT1A6 (80% identical), mouse Ugt1a9 (79% identical), mouse Ugt1a10 (79% identical), mouse Ugt1a7c (79% identical), mouse Ugt1a8 (78% identical), zebrafish ugt2a7 (40% identical), zebrafish ugt2b1 (39% identical), zebrafish ugt2b5 (38% identical), zebrafish si:ch73-334d15.1 (38% identical), zebrafish ugt5g1 (36% identical), zebrafish ugt5c1 (36% identical), zebrafish ugt5c3 (36% identical), and 98 more. Paralogues in human: UGT1A8 (95% identical), UGT1A7 (93% identical), UGT1A10 (93% identical), UGT1A5 (69% identical), UGT1A3 (69% identical), UGT1A4 (68% identical), UGT1A6 (68% identical), UGT1A1 (68% identical), UGT2B10 (44% identical), UGT2B17 (43% identical), UGT2B4 (43% identical), UGT2B11 (43% identical), and 9 more.
Diseases named in the same sentence as UGT1A9 in open-access papers:
UGT1A9 is named in the same sentence as 51 diseases in open-access papers, as found by Europe PMC text mining. Sharing a sentence is not in itself a finding about the gene and the disease. The quoted sentences say what the papers report.
neutropenia (6 papers, 2010 to 2022). A decrease in the number of neutrophils found in the blood. "When treating high-risk patients with the UGT1A9*22 polymorphism, clinicians should closely monitor them for signs of toxicity such as severe diarrhea or neutropenia." (PMID 36239106, 2022). "It has previously been reported that UGT1A9*22 variants have a lower risk of suffering irinotecan-induced severe neutropenia." (PMID 28637434, 2017). "This Korean irinotecan pharmacokinetics study might also explain our finding that UGT1A1*6, UGT1A7*3, and UGT1A9*22 were associated with severe diarrhea or neutropenia." (PMID 36239106, 2022). "Furthermore, inherited genetic variations in UGT1A1, UGT1A7 and UGT1A9 are associated with grade 3/4 neutropenia." (PMID 25202427, 2014). "In patients who experienced grade III–IV neutropenia, the UGT1A1*6, UGT1A7*3 and UGT1A9*22 polymorphisms showed significant associations only among those who received the weekly regimen (p = 0.015, p = 0.042, and p = 0.024, respectively)." (PMID 36239106, 2022). "Among patients who had any of the UGT1A1*6, UGT1A7*3 or UGT1A9*22 variants, 13 suffered grade III–IV neutropenia and 23 suffered grade III–IV diarrhea." (PMID 36239106, 2022). "Although only about 20% to 30% of patients who had the UGT1A9*22 polymorphism suffered severe toxicity, by classifying these patients as a high-risk group for irinotecan toxicity, clinicians could follow these patients more closely for severe diarrhea or neutropenia." (PMID 36239106, 2022). "The patients with UGT1A1*6 and UGT1A7*3 were prone to severe neutropenia, and the patients with UGT1A9*1b were prone to severe diarrhea." (PMID 29609559, 2018). "UGT1A1*6, UGT1A7*3 and UGT1A9*1b should be monitored regularly to avoid the incidence of the severe neutropenia and diarrhea." (PMID 29609559, 2018). "Since variants of not only UGT1A1, but also other genes, including UGT1A7, UGT1A9, ABCB1 and ABCC2, have been reported to be involved in the occurrence of CPT-11-induced severe neutropenia, rare variants of these genes should be investigated in the future." (PMID 24932285, 2014). "Furthermore, the H2 haplotype, which includes UGT1A9*22, and the H5 and H7 haplotypes, which include UGT1A7*2, UGT1A7*3 and UGT1A7*4, were associated with an increased risk of severe neutropenia." (PMID 25202427, 2014). "Additionally, H2 haplotypes, which include UGT1A9*22, and H5 and H7 haplotypes, which include UGT1A7*2, UGT1A7*3 and UGT1A7*4, were associated with a higher risk of severe neutropenia." (PMID 25202427, 2014). "Patients with the UGT1A9*1/*1 genotype were more likely to develop severe non-haematologic toxicity and diarrhoea, whereas UGT1A7*3/*3 genotype was also associated with the occurrence of neutropenia and diarrhoea simultaneously." (PMID 20628391, 2010).
colon cancer (5 papers, 2013 to 2024). "Colon cancer cells were pretreated with propofol or UGT1A siRNA to inhibit UGT1A9 activity and then exposed to 5 μM of β-lap for 24 h." (PMID 25692465, 2015). "We show in the present study that the expression level of UGT1A, and in particular UGT1A9, is an important factor in determining the intracellular accumulation and the apoptotic effect of TSA in human colon cancer cells." (PMID 24244442, 2013). "Research has shown that DAPA has potential anticancer effects on colon cancer cells expressing SGLT2 but not UGT1A9 because cancer HCT116 cells express SGLT2 but not UGT1A9." (PMID 38595915, 2024). "Dapagliflozin has been demonstrated to have a possible inhibitory effect on colon cancer cells that express SGLT2 but not UDP glucuronosyltransferase family 1 member A9 (UGT1A9)." (PMID 37047011, 2023). "Concomitant with these lines of results, we experienced that CEA in patients with colon cancer, which express SGLT2 but not UGT1A9, and type 2 diabetes mellitus treated by dapagliflozin in addition to chemotherapy was decreased (case 1)." (PMID 31979355, 2020). "Taken together, these data suggest a potential role for dapagliflozin anticancer therapy against colon cancer cells that express SGLT2, but not UGT1A9." (PMID 31979355, 2020). "CEA in patients with colon cancer, which express SGLT2 but not UGT1A9, and type 2 diabetes mellitus was treated by dapagliflozin alone after radiation therapy was decreased but started to rise after cessation of dapagliflozin (case 2)." (PMID 31979355, 2020).
colorectal cancer (4 papers, 2011 to 2024). A primary or metastatic malignant neoplasm that affects the colon or rectum. "The UGT1A1*6, UGT1A7*3 and UGT1A9*22 genotypes were shown to be related to severe toxicity concordant with a Japanese study of FOLFIRI-treated colorectal cancer patients." (PMID 36239106, 2022). "Studies have also indicated that the UGT1A7 and/or UGT1A9 genotypes may be predictors of response and toxicity in colorectal cancer (CRC) patients treated with capecitabine and irinotecan." (PMID 39717480, 2024). "Interestingly, overexpression of PXR in the colorectal cancer tissue samples was correlated with an increase in UDP glucuronosyl transferases UGT1A1, UGT1A9 and UGT1A10, and led to a marked chemoresistance to the active metabolite of irinotecan (CPT-11)." (PMID 21342487, 2011).
hepatocellular carcinoma (3 papers, 2017 to 2022). A malignant tumor that arises from hepatocytes. "Genetic polymorphisms of TNF-α, VEGF, and UGT1A9 genes have been reported to be a link between HFSRs in patients with hepatocellular carcinoma treated with sorafenib." (PMID 28487491, 2017). "Similarly, in patients with hepatocellular carcinoma treated with sorafenib after surgery, those with good prognosis had high UGT1A9 expression." (PMID 36741721, 2022).
Pancreatic Cancer (3 papers, 2017 to 2022). "The interplay between UGT enzymes and lipid homeostasis is also supported by the perturbed accumulation of lipid droplets induced by the expression of UGT1A9 and UGT2B7 in HEK293, breast and pancreas cancer cell models." (PMID 36295907, 2022). "Along with six other top DEGs, i.e. TINAG, LINC00460, UGT1A9, SLCO1B7, HOTTIP, and ALCO1B3, their expression status could not be found in the Pancreatic Cancer Database." (PMID 28418924, 2017).
Hyperbilirubinemia (2 papers, 2014 to 2019). An increased amount of bilirubin in the blood. "Hyperbilirubinemia higher than grade 2 was significantly associated with the uridine diphosphate glucuronosyltransferase (UGT)1A9 I399C/C genotype (P = 0.0086; Odds Ratio, 21.2; 95% Confidence Interval 2.2–208.0)." (PMID 24650752, 2014). "Furthermore, in IM-resistant patients treated by the second-generation TKI, nilotinib, some UGT1A9 variants affected nilotinib efficacy and were associated with adverse events (hyperbilirubinemia)." (PMID 31470908, 2019). "However, we are not aware of any studies that have examined a correlation between hyperbilirubinemia and the UGT1A9 I399C > T polymorphism." (PMID 24650752, 2014). "Hyperbilirubinemia may be predicted before nilotinib treatment, and may be controlled by reducing the daily dose of nilotinib in patients with UGT1A9 polymorphisms." (PMID 24650752, 2014). "Our study suggests that hyperbilirubinemia is associated with the UGT1A9 I399C/C genotype." (PMID 24650752, 2014). "For Japanese patients with CML, hyperbilirubinemia may be predicted before nilotinib treatment and controlled by reducing the daily dose of nilotinib in patients with UGT1A9 polymorphisms." (PMID 24650752, 2014). "However, to our knowledge this is the first report of a significant correlation between hyperbilirubinemia and the UGT1A9 I399C/C genotype." (PMID 24650752, 2014).
Hypertension (2 papers, 2017 to 2019). The presence of chronic increased pressure in the systemic arterial system. "Genetic variants VEGFR2 rs2239702, ABCB1 rs1045642 and ABCB1 rs2032582 were significantly associated with increased risk of HFS and hypertension; ABCB1 rs1128503 was reported associated with increased risk of hypertension; UGT1A1*6 rs4148323 and UGT1A9 were associated with hypertension." (PMID 28404979, 2017). "Among the superfamily of UGT enzymes, UGT1 is strongly engaged in the metabolism of drugs used to treat epilepsy (UGT1A4), schizophrenia (UGT1A3 and UGT1A4), hypertension (UGT1A1, UGT1A3, UGT1A7, and UGT1A9), and hypercholesterolemia (UGT1A1 and UGT1A3)." (PMID 30959953, 2019).
liver dysfunction (2 papers, 2016 to 2023). "In future investigations, the exploration of polymorphism in some enzymes such as CYP3A4 and UGT1A9 may be useful to predict the sorafnib-induced liver dysfunction." (PMID 26943680, 2016).
metastatic colorectal cancer (2 papers, 2014). "UGT1A1*6 (211G>A), UGT1A1*28 (TA6>TA7), UGT1A1*60 (−3279T>G), UGT1A7 (387T>G), UGT1A7 (622T>C), and UGT1A9*1b (−118T9>T10, also named *22) were genotyped in 123 patients with metastatic colorectal cancer who had received irinotecan-based chemotherapy." (PMID 25175642, 2014).
non-small cell lung carcinoma (2 papers, 2021 to 2022). A group of at least three distinct histological types of lung cancer, including non-small cell squamous cell carcinoma, adenocarcinoma, and large cell carcinoma. "Non-small cell lung cancer patients with the UGT1A9 rs3832043 T9/T9 genotype, which resulted in the deletion of the thymine nucleotide in the −118 promotor sequence of the UGT1A9 gene, had decreased gene expression and hence reduced glucuronidation capacity of UGT1A9." (PMID 34198586, 2021).
Obesity (2 papers, 2023 to 2024). Accumulation of substantial excess body fat. "From UDP-D-glucuronate to D-glucuronate, Ugt1a9 and Ugt2b1 genes are involved, the expression of Ugt1a9 and Ugt2b1 was downregulated, and the content of D-glucuronate was decreased in obese kidney, suggesting that obesity can affect ascorbate biosynthesis." (PMID 38603672, 2024). "Of note, UGT1A6 and UGT1A9 are the main UGT isoforms involved in APAP glucuronidation in humans but only UGT1A9 protein expression tended to be increased in patients with obesity-related fatty liver." (PMID 36713231, 2023).
acute pyelonephritis (1 paper, 2023). "This study reported, for the first time, reductions in the in vivo activities of the renal transporters OAT1/3 (~40%) and UGT1A9/1A1 (~50%) due to systemic inflammation caused by acute pyelonephritis." (PMID 37896187, 2023). "In conclusion, the data from this paired study showed that systemic inflammation, due to a bacterial infection caused by acute pyelonephritis, reduced the in vivo activity of the renal transporters OAT1/3 and renal UGT1A9/1A1 in pregnant women by approximately 40% and 50%, respectively." (PMID 37896187, 2023).
colitis (1 paper, 2022). Inflammation of the colon. "We confirmed that protein expression of UGT1A1 and UGT1A9 were consistently suppressed in the liver of colitis mice." (PMID 36408246, 2022). "PXR was the only UGT regulator significantly downregulated in colitis mice, suggesting dysregulation of PXR is associated with the downregulation of UGT1A1 and UGT1A9, thereby potentially resulting in dysfunction of baicalein and puerarin glucuronidation." (PMID 36408246, 2022). "Downregulation of PXR in colitis is associated with dampened UGT1A1 and UGT1A9, thereby potentially resulting in dysfunction of flavonoid glucuronidation." (PMID 36408246, 2022). "Dysregulation of PXR in colitis is associated with the downregulation of UGT1A1 and UGT1A9, thereby potentially resulting in dysfunction of baicalein and puerarin glucuronidation." (PMID 36408246, 2022). "In the current study, we observed that the downregulation of PXR in colitis is associated with suppressed UGT1A1 and UGT1A9." (PMID 36408246, 2022). "Secondly, Ugt1a1 and Ugt1a9 are consistently suppressed in the Il-10−/− spontaneously develop colitis mice as compared to the control mice." (PMID 36408246, 2022). "Altogether, downregulation of hepatic UGT1A1 and UGT1A9 in colitis leads to dampened flavonoid glucuronidation." (PMID 36408246, 2022). "Taken together, these findings indicate that deregulation of PXR in colitis is associated with the downregulation of UGT1A1 and UGT1A9, thereby potentially resulting in dysfunction of flavonoid glucuronidation." (PMID 36408246, 2022). "Among the UGT1A1 and UGT1A9 regulators, only Pxr was significantly downregulated in colitis mice, suggesting dysregulation of PXR in colitis is associated with the downregulation of UGT1A1 and UGT1A9, thereby potentially resulting in dysfunction of baicalein and puerarin glucuronidation." (PMID 36408246, 2022). "We thus investigated how these nuclear receptors mediate colitis-regulated UGT1A1 and UGT1A9 in the liver." (PMID 36408246, 2022). "Twelve UGTs were downregulated in the liver of colitis mice including UGT1A1 and UGT1A9 (two representative UGTs)." (PMID 36408246, 2022). "We thus established a DSS-induced colitis model to determine the effects of colitis on UGT1A1 and UGT1A9 in various tissues." (PMID 36408246, 2022). "Firstly, 1 day of DSS administration is insufficient to induce colitis and does not alter the expression of Ugt1a1 and Ugt1a9." (PMID 36408246, 2022). "Moreover, we observed that colitis-reduced UGT1A1 and UGT1A9 led to dampened baicalein and puerarin glucuronidation." (PMID 36408246, 2022). "In addition, UGT1A1 and UGT1A9 were downregulated in a genetic colitis model (Il-10−/− spontaneously develop colitis), which is in accordance with the results of the DSS-induced colitis model." (PMID 36408246, 2022). "Colitis in mice downregulates UGT1A1 and UGT1A9 in the liver but not in other metabolic tissues, indicating colitis-induced dysregulation pattern of UGTs is specifically occurring in the liver." (PMID 36408246, 2022). "Moreover, colitis-reduced UGT1A1 and UGT1A9 lead to dampened baicalein and puerarin glucuronidation." (PMID 36408246, 2022). "Therefore, the inhibitory effects of colitis on UGT1A1 and UGT1A9 could be time-varying." (PMID 36408246, 2022). "Colitis in mice downregulated UGT1A1 and UGT1A9 in the liver but not in small intestine, colon, and kidney." (PMID 36408246, 2022).
cytomegalovirus infection (1 paper, 2023). A herpesvirus infection caused by Cytomegalovirus. "Similarly, a higher plasma exposure (~70%) to the immunosuppressive mycophenolate mofetil (primarily metabolized by hepatic UGT1A9) was observed in transplanted patients with a cytomegalovirus infection, an inflammatory viral disease." (PMID 37896187, 2023).